KLRG1 (killer cell lectin like receptor G1)
Diseases named in the same sentence as KLRG1 in open-access papers (continued):
Sharing a sentence is not in itself a finding about the gene and the disease.
Obesity (1 paper, 2021). Accumulation of substantial excess body fat. "To determine whether diet-induced obesity (DIO) affects KLRG1 expression on CD8+ T cells, we performed flow cytometry on immune cells isolated from HFD or ND-fed mice." (PMID 34248964, 2021).
Pcc (1 paper, 2023). "Further studies will be required to determine whether these cells can replenish CD127+KLRG1− and CD127−KLRG1+ populations during Pcc chronic infection." (PMID 37855243, 2023).
periodontitis (1 paper, 2018). An acute or chronic inflammatory process that affects the tissues that surround and support the teeth. "exFoxp3T cells in periodontitis-induced mice expressed regulatory T (Treg) cell signature molecules such as GITR, KLRG1, FR4, and Nrp1 to a similar extent to GFP+YFP+ T cells while GFP–YFP– T cells expressed these genes at a lower level." (PMID 29453398, 2018).
primary immunodeficiency (1 paper, 2024). "The high KLRG1 subgroup showed enrichment in folate biosynthesis, phenylalanine metabolism, and riboflavin metabolism, while the low KLRG1 subgroup was enriched in homologous recombination, primary immunodeficiency, and steroid biosynthesis." (PMID 39867577, 2024).
psoriasis (1 paper, 2020). An autoimmune condition characterized by red, well-delineated plaques with silvery scales that are usually on the extensor surfaces and scalp. "However, the role of NK cells in psoriasis mouse models remains unclear, although NK cell maturation markers, such as CD11b, CD43, CD27, and killer cell lectin-like receptor G1 (KLRG1), increase in peripheral blood and spleen NK cells from imiquimod-treated mice." (PMID 32917058, 2020).
psoriatic arthritis (1 paper, 2026). Joint inflammation associated with psoriasis. "The increase in CD27 and OX40 expression across both subsets indicates chronic antigen experience, while the selective rise in 2B4 and KLRG1 within γδT cells in psoriatic arthritis is compatible with repeated stimulation and effector skewing described for chronically engaged γδT populations." (PMID 41596369, 2026).
sarcoidosis (1 paper, 2025). Sarcoidosis is a multisystemic disorder of unknown cause characterized by the formation of immune granulomas in involved organs. "By contrast, T cells from sarcoidosis patients exhibited clonal expansion of terminally differentiated CD8+ effectors that expressed high levels of effector genes, including CCL5, GZMB, PRF1, IFNG, KLRG1 and ZEB2." (PMID 40469525, 2025).
skin infection (1 paper, 2020). An inflammatory process affecting the skin, caused by bacteria, viruses, parasites, or fungi. "In early skin infection of herpes simplex virus, skin-infiltrating T cells are mainly KLRG1+ effector cells, while at the memory phase, the remaining memory T cells in the skin bear negative or low expression of KLRG1." (PMID 33633737, 2020).
Splenomegaly (1 paper, 2025). Abnormal increased size of the spleen. "In agreement with the increased production of pro-inflammatory cytokines, we found that mice transferred with KLRG1+ Treg cells showed splenomegaly together with increased percentages of circulating neutrophils and basophils compared with noninjected or mice injected with KLRG1− Treg cells." (PMID 40307497, 2025).
vitiligo (1 paper, 2021). Generalized well circumscribed patches of leukoderma that are generally distributed over symmetric body locations and is due to autoimmune destruction of melanocytes. "Some cytokines such as KLRG1+ lymphocytes secrete cytotoxic molecules (granzyme B and perforin), inflammatory cytokines (IFN-γ and TNF-α), and inflammatory chemokine receptors (CCR5 and CX3CR1) are involved in gene expression, which are associated with vitiligo." (PMID 33679890, 2021).
tumor (184 papers, 2010 to 2026). "Of importance, whereas frequencies of terminal mature CD27-CD11b+KLRG1+ NK cells in the spleen were still reduced in Nr2f6-deficient mice, they were rescued to wild-type controls in the blood and the tumor." (PMID 39920136, 2025). "Other NK receptors recognize tumor‐associated antigens (NKp30, NKp44, NKp46), cell–cell adhesion proteins (KLRG1, CD96), or genetically coupled C‐type lectin‐like ligands (NKp65, NKR‐P1)." (PMID 39748148, 2025). "The reduction of e-cadherin in tumor cells leads to loss of killer cell lectin-like receptor G1 (KLRG1) expression in ILC2s, and this KLRG1- ILC2s subgroup secretes more CXCL2 recruitment neutrophils to form an immunosuppressive microenvironment." (PMID 39309440, 2024). "But an article reported that KLRG1+effector CD8+T cells can effectively promote anti-tumor immunity after differentiation and loss of KLRG1 expression." (PMID 35265614, 2022). "The treatment of tumor-bearing mice with a combination of anti-PD-1 and anti-KLRG1 antibodies further improved the anti-tumor response and was associated with increased intratumor T and NK cell accumulation compared to single treatments." (PMID 34885076, 2021). "We further demonstrate that this is associated with increased CCR2 expression by KLRG1+ NK cells from Ackr2−/− mice and attendant hyperresponsiveness of these cells to tumor-expressed CCL2." (PMID 30158126, 2018). "In this study, we examined the roles of KLRG1 in human T cells and the underlying mechanism, especially in the tumor microenvironment." (PMID 27557510, 2016). "Indeed, in cancer cells the dysregulation of immune checkpoint proteins is an important mechanism of tumor immune resistance and KLRG1 has been associated with both solid and hematological malignancies." (PMID 40303366, 2025). "Thus, KLRG1 is a diagnostic marker for isolation and further study of tumor-matching, cytotoxic CD4+ T cell clones from the periphery of patients with cancer." (PMID 40299576, 2025). "Conversely, THEM4, TDRD9, and KLRG1, which act as risk factors in some cancers, might contribute to tumor progression through immune evasion mechanisms or by impairing apoptosis pathways." (PMID 39867577, 2024). "For instance, BCL7A and GRB10 showed protective roles in some cancers, possibly through mechanisms such as enhancing immune infiltration or suppressing oncogenic pathways, while THEM4, TDRD9, and KLRG1 acted as risk factors in others, potentially by inhibiting tumor suppressor functions." (PMID 39867577, 2024). "In the tumor context, KLRG1 expression was found on ILC2 associated to the tumor in NSCLC and CRC." (PMID 31105707, 2019). "Thus, we examined if tumor regression was associated with the triple therapy's ability to drive robust tumor infiltrating KLRG1+ effector memory Ag-specific CD8+ T cell responses." (PMID 28388572, 2017). "Many co-stimulatory and inhibitory molecules were found increased expression in low-risk patients, as well as T cell activation markers such as KLRG1, which might imply a hyporesponsive state of T cells in tumor-killing activities that decrease tumor burden to improve survival." (PMID 39478862, 2024). "Collectively, these data suggest that mRNA levels of VISTA, TIGIT and KLRG1 in CRC tumor tissues could be elevated in CRC patients with high grades of tumor budding, which is considered as a risk factor for poor disease prognosis and metastasis in CRC patients." (PMID 32393998, 2020). "We found that KLRG-1 expression is also associated with C6 and we found cells displaying C6-like characteristics among T cells specific for mAlg8 after immunotherapy at comparable levels to the frequencies of mAlg8-specific T cells derived from isotype control treated tumour bearing animals." (PMID 28916749, 2017). "Prior work from our group showed that the inhibitory receptor KLRG1 binds to tumor-derived E-cadherin." (PMID 42030532, 2026).
tumor (continued). "Within the tumour microenvironment, the majority of CD8+ T cells in the NIR-PIT and combination groups were Klrg1-positive, suggesting that most tumour-infiltrating CD8+ T cells had differentiated into effector cells following treatment." (PMID 40792441, 2025). "The anti-correlation of PD-1 and KLRG1 expression in human tumor infiltrating CD8 T cells suggests the potential for combination therapy supra-additive benefits of anti-PD-1 and anti-KLRG1 therapies." (PMID 39832302, 2025). "Specifically, recent studies demonstrate that KLRG1+ ILC2s can acquire anti-tumor functions through IL-10 production and IL-33–mediated activation." (PMID 40497988, 2025). "This latter observation suggests that adding KLRG1 blockade to PD-1 blockade can further mobilize additional tumor-TCR-matching cytotoxic CD4+ T cells in the periphery to kill." (PMID 40299576, 2025). "The anti-tumor effects of KLRG1 blockade has relatively recently been demonstrated in preclinical in vivo studies." (PMID 39832302, 2025). "This showed that KLRG1+ sorted cells have a higher proportion of tumor-matching TCRs compared with KLRG1– sorted cells." (PMID 40299576, 2025). "Studies have shown that KLRG1 knockdown affects tumor cell proliferation, highlighting its potential as a therapeutic target." (PMID 40654678, 2025). "To test this, we expanded KLRG1+ and KLRG1– T cells from PBMCs and tumors of the same patient, coincubated with autologous tumor cells, and measured tumor cell killing." (PMID 40299576, 2025). "Within the NKim subcluster, gene expression of key receptors and cytokines (Il15, CXCR3, KLRG1) correlated significantly with tumor grade." (PMID 40821787, 2025). "Similar patterns of perforin expression were seen also for cytotoxic CD8+ T cells in untreated patients, except their GZMB-only expressing cells were less regulated by KLRG1 in tumor." (PMID 40299576, 2025). "Specifically, recent studies have demonstrated that KLRG1+ ILC2s can acquire anti-tumor functions through IL-10 production and IL-33–mediated activation." (PMID 40497988, 2025). "ILC1s and NK cells express inhibitory receptors, such as natural killer group 2 member A (NKG2A), Killer cell lectin-like receptor G1 (KLRG1), and other inhibitory receptors, which contribute to tumor advancement in an immunosuppressive TME." (PMID 40497988, 2025). "Subsequently, the comparison of the mean fluorescence intensity (MFI) values of ST2 and KLRG1 expressed by ILC2s from the spleens and tumor tissues of the tumor-bearing mice also confirmed this." (PMID 38430390, 2024). "Among BRD4 targets, we also identified CEACAM1, which was reported to inhibit NK-mediated cytolysis of tumor cells and KLRG1, a negative regulator of CD8+ lymphocytes and NK cells." (PMID 38519469, 2024). "Similar results were also seen in WT and ADAM17 KO CD8+ TILs from the direct tumor model, as well as in KLRG1+CD127- CD8+ SLECs from the in vivo acute infection model." (PMID 38918390, 2024). "Blocking KLRG1 has been shown to effectively mitigate the effects of downregulation in various mouse tumor models, including solid tumors and hematologic malignancies." (PMID 38898461, 2024). "Our results showed that tumor-derived ILC2s were in the rest state with nearly undetectable KLRG1 and ST2 compared with spleen-, and lung-derived ILC2s." (PMID 38430390, 2024). "As a ligand of KLRG1, cadherin is widely expressed on antigen-presenting cells (APCs) and tumor cells and binds to the extracellular domain to achieve signal transduction." (PMID 38898461, 2024). "This interaction between N-cadherin and KLRG1 impairs NK cell functions, facilitating the circulation and seeding of new tumors by the tumor cells." (PMID 39192980, 2024). "Consistent findings were observed in human samples, where a reduced infiltration of Lin− KLRG1+ cells was detected in tumor tissues compared to para-carcinoma tissues." (PMID 38430390, 2024).
tumor (continued). "KLRG1 can bind to ligands and play an important role in tumor development by regulating lymphocyte activity, inhibiting cytokine secretion, and inducing apoptosis to suppress the immune response." (PMID 38898461, 2024). "In the tumor microenvironment, KLRG1 can inhibit the antitumor immune response and promote tumor escape." (PMID 38898461, 2024). "We have also demonstrated infiltration of CD45, Macrophages, and NK cells into the tumor stroma, and upregulation of KLRG1, Sell, Ccr7, and IL7r upon the treatment with ICG-001 and then CAR Ts." (PMID 38449858, 2024). "In CRC patients, the mRNA expression level of KLRG1 was significantly greater in tumor tissues than in paired normal tissues and tended to increase in the advanced stages of the disease." (PMID 38898461, 2024). "It is foreseeable that the emergence of future anti-KLRG1 drugs will lead to the development of new treatment strategies for tumor suppressor receptor immunotherapy." (PMID 38898461, 2024). "First, while KLRG1 expression has been detected in various cell types, including tumor cells, a systematic and comprehensive summary of the potential mechanisms underlying its role is lacking." (PMID 38898461, 2024). "In the presence of tumours, frequency of C2 Klrg1+ inflammatory cluster is drastically reduced from 19% in naïve-ILC2s to nearly 0 in ta-ILC2s in the mouse lungs." (PMID 38172434, 2024). "Overall, KLRG1 can inhibit the antitumor activities of immune cells, promote tumor metastasis, and lead to immune dysfunction in patients." (PMID 38898461, 2024). "The anti-tumor activity of tumor-infiltrating T cells and peripheral blood T cells is dramatically up-regulated in mice treated with the anti-KLRG1 antibody." (PMID 36703228, 2023). "In contrast, in the spleen, the Cxcr3+ Klrg1+ intermediate population was quite rare, especially when comparing to the proportion of Cxcr3+ Klrg1+ tumor-specific (tetramer-binding) T cells." (PMID 36472588, 2023). "In corroboration with our findings, blockades of CD38 and KLRG1 are being developed as therapeutic strategies to promote tumor immunity and to ameliorate resistance to PD-1/PD-L1 checkpoint inhibitors and other cancer therapies." (PMID 37207205, 2023). "Over time, Cxcr3 and Klrg1 were progressively decreased on tumor-specific T cells infiltrating PDA and these Cxcr3-Klrg1- T cells co-expressed PD-1 and Lag-3, markers that identify TEX cells defective in IFNγ production." (PMID 36472588, 2023). "We previously showed that Batf3 + Xcr1 + cDC1s are required to not only prime tumor-specific CD8 T cells in the spleen, but also maintain adoptively transferred Klrg1 + effector T cells in both spleen and tumor." (PMID 36472588, 2023). "KLRG1, KLRG1 were upregulated in human tumor samples and potentially contributing to adaptive resistance, KLRG1 blockade was found to be effective at slowing tumor growth." (PMID 37325644, 2023). "IL-7Rα and KLRG-1 surface markers were used to differentiate the two stages of T cell differentiation at the effector phase of the anti-tumor response: short-lived effector cells (SLECs) and memory precursor effector cells (MPECs)." (PMID 37033927, 2023). "To gain insight into the dynamics of the therapy-responsive T cell subsets, we longitudinally followed the CD431B11+, NKG2A+, and KLRG1+ T cell subsets in the blood circulation of ICT-treated MC-38 tumor-bearing mice." (PMID 36796366, 2023). "We identify a Cxcr3+ Klrg1+ intermediate T cell subpopulation in the spleen that is highly enriched for tumor specificity." (PMID 36472588, 2023). "Here, we show in the spleen of tumor-bearing mice early on during tumor establishment, most tetramer + T cells expressed Cxcr3 and/or Klrg1 and the intermediate Cxcr3+ Klrg1 + subpopulation in the spleen is particularly enriched for tumor antigen specificity." (PMID 36472588, 2023). "In both Cxcr3+/+ and Cxcr3−/− mice, tumor-infiltrating T cells upregulated PD-1 and Lag3 and lost Klrg1 as compared to splenic tetramer + T cells." (PMID 36472588, 2023).
tumor (continued). "This trend in cell ratios reflects the possibility that CD127-expressing T cells and KLRG1-expressing CD8+ T cells are the main immune cell types mediating anti-tumor immunity after the addition of PD-1 blockade to neoadjuvant chemotherapy." (PMID 37231145, 2023). "Cxcr3 promoted the differentiation of Klrg1 + PDA-specific T cells in the spleen of tumor-bearing mice, consistent with Cxcr3 promoting short-lived effector T cells in acute infection models." (PMID 36472588, 2023). "Here, in cDC1-deficient hosts, CD40 agonist primed tumor-specific T cells that coexpressed Klrg1 and Lag3, or a Treg marker Foxp3, and these T cells appeared dispensable for tumor control." (PMID 35393950, 2022). "We propose that when designing anti-tumor therapies targeting KLRG1, the effects on both effector cells and Tregs will have to be considered." (PMID 35572605, 2022). "The cancer-promoting and cancer-suppressing effects of KLRG1 appear paradoxical in response to immunotherapy and the effects of the cell cycle of the tumor cells themselves." (PMID 35265614, 2022). "CD40 agonist promotes the accumulation of the functional intratumoral Klrg1+ subset in PDA in wild-type tumor-bearing mice." (PMID 35393950, 2022). "Altogether, these results showed that ILC2s, which downregulate KLRG1 in the HCC tumor microenvironment, promote HCC via CXCL2-dependent neutrophil recruitment and IL-13-driven immunosuppression." (PMID 35281021, 2022). "NK cells also displayed a biased maturation profile toward CD27-CD11b+ NK cells as well as increased proportion of KLRG1+ cells in Bach2cKO mice compared to control mice after tumor challenge." (PMID 36190189, 2022). "While the role for cDC1s influencing prototypical exhaustion markers is less clear, cDC1s promote endogenous Klrg1+ tumor-specific T cell expansion and thus a reservoir of functional tumor-specific T cells." (PMID 35393950, 2022). "In support of these findings, our lab also reported that infiltration of KLRG1+ Tregs directly correlates with tumor size." (PMID 35572605, 2022). "Conditional cDC1 depletion significantly decreased splenic Klrg1+ and intratumoral Lag3+ tumor-specific T cell frequency." (PMID 35393950, 2022). "The combination therapy increased CD8+:CD4+ ratios and led to an increase in serine protease granzyme B, Ki67, and killer cell lectin like receptor G1 (KLRG1) in tumor infiltrating CD8+ cells." (PMID 36203599, 2022). "The role of cadherins on tumor immunosurveillance by KLRG1+ tumor infiltrating lymphocytes is just beginning to be investigated." (PMID 35572605, 2022). "Altogether, the data support strategies aiming at targeting KLRG1+ Treg quantity and activity to improve anti-tumor immunity." (PMID 35572605, 2022). "Particularly, cDC1s supported a reservoir of splenic Klrg1+ cytotoxic T cells, which based on our prior work, are likely necessary for long-term tumor control." (PMID 35393950, 2022). "Host cDC1s reactivate transferred effector and memory T cells to promote splenic Klrg1+ T cells and tumor control." (PMID 35393950, 2022). "Regarding cancer, recent studies have demonstrated a role for KLRG1 on effector cells in anti-tumor immunity." (PMID 35572605, 2022). "To specifically define the role of KLRG1 on NK cells or Tregs in a variety of murine tumor models, we have begun to cross KLRG1 floxed mice to Ncr-Cre and Foxp3-Cre respectively." (PMID 35572605, 2022). "In our prior studies, most tumor-specific T cells diverged into Lag3+ TEX in PDA or remained Klrg1+ functional cytotoxic T cells in the spleens of tumor-bearing mice." (PMID 35393950, 2022). "Among Kb-SIINFEKL+ CD8+ T cells, KLRG1+ effector T cells were also increased in both the tumor and spleen by mJX-594 treatment." (PMID 35453555, 2022). "Our results support that cDC1s are required for the reactivation of tumor-specific memory T cells, resulting in their differentiation into the Klrg1+Lag3– effector subset, which appear critical for tumor control." (PMID 35393950, 2022).